TRAJ40 (T cell receptor alpha joining 40)
Gene: T-cell receptor joining (J) gene on chromosome 14 (22,499,689 to 22,499,749, forward strand). Ensembl gene ENSG00000211849.
Diseases named in the same sentence as TRAJ40 in open-access papers:
TRAJ40 is named in the same sentence as 1 disease in open-access papers, as found by Europe PMC text mining. Sharing a sentence is not in itself a finding about the gene and the disease.
TRAJ40 shares sentences with these, for which no sentence is quoted: colitis (1 paper).